IL33 (interleukin 33)
Diseases named in the same sentence as IL33 in open-access papers (continued):
Sharing a sentence is not in itself a finding about the gene and the disease.
atopic dermatitis (continued). "Serum IL-33 levels are higher in atopic dermatitis patients compared with healthy individuals and it correlates with excoriation and xerosis scores in atopic dermatitis." (PMID 35432341, 2022). "Except for respiratory allergies, IL-33 is predominant in ILC2-inducing type 2 cytokines in atopic dermatitis." (PMID 36291105, 2022). "IL-33 has been reported to be highly expressed in several skin diseases, including atopic dermatitis, psoriasis, and vitiligo." (PMID 35432341, 2022). "TSLP-elicited ILC2 promotes allergic inflammation, whereas IL-25 and IL-33 are dispensable for this ILC2 response in an atopic dermatitis-like mouse model." (PMID 35432341, 2022). "In a phase 2 clinical trial of etokimab (anti-IL-33 mAb), atopic dermatitis patients had significantly reduced neutrophil migration in a CXCR1 dependent manner." (PMID 34266437, 2021). "For example, IL-22, IL-23, IL-31, and IL-33 were increased in the skin of patients and model animals with allergic dermatitis, AD, and psoriasis." (PMID 33708782, 2021). "Second, initial data have demonstrated that blocking HMGB1 is effective in ameliorating psoriasis similar to blocking some other alarmins (e.g., IL-33) in other chronic inflammatory skin diseases (e.g., atopic dermatitis)." (PMID 35053208, 2021). "The proinflammatory role is supported by correlation of serum IL-33 with disease severity in atopic dermatitis and through disease attenuation with IL-33 inhibition in murine allergic asthma." (PMID 33884963, 2021). "As such, clinical trials are investigating the effectiveness of neutralizing IL-33 in severe asthmatics and those with moderate-to-severe atopic dermatitis." (PMID 34266437, 2021). "In transgenic mice expressing interleukin 33 with atopic dermatitis symptoms, ILC2s were greatly increased in the lesional skin, regional lymph nodes, and peripheral blood." (PMID 32326002, 2020). "There are several possible reasons for the clear discrepancies on the role of IL-33 in calcipotriol model of atopic dermatitis." (PMID 32296080, 2020). "It is known that both IL-31 and IL-33 initiate skin inflammation and lead to the dysregulation of immunomodulatory proteins in atopic dermatitis through STAT3 pathway activation." (PMID 32566105, 2020). "A phase 2a study of a single intravenous 300 mg dose of etokimab, a humanized IgG1/kappa anti–IL-33 monoclonal, in 12 adult patients with moderate-to-severe atopic dermatitis, has recently been published." (PMID 32679721, 2020). "Higher serum levels of IL-33 were also found in atopic dermatitis, generalized vitiligo, or Still's disease." (PMID 32377165, 2020). "IL33 has been shown to accumulate in inflamed skin in a mouse model of poison ivy-induced allergic dermatitis and contribute to itching." (PMID 33224151, 2020). "ILCs in the skin are activated by TSLP, IL-33, and IL-25, which are highly expressed in atopic dermatitis." (PMID 32326002, 2020). "Activation of ST2 and ILC2s in keratinocytes and overexpression of IL-33 can lead to the development of atopic dermatitis." (PMID 32566105, 2020). "Although IL-33 confers beneficial host defenses, its role in the progression of auto-inflammatory disorders like asthma, rhinosinusitis, obesity, atopic dermatitis, and lung fibrosis are apparent." (PMID 31574995, 2019). "IL-33 was always described as a cytokine that induces Th2 response, as it was suggested by many papers of its involvement in allergic skin disease and atopic dermatitis." (PMID 31736655, 2019). "In contrast, studies on atopic dermatitis (AD), an inflammatory skin disorder showed that the production of IL-33 was driven by inflammation signaling mechanisms." (PMID 30205617, 2018). "The cytokine interleukin 33 (IL-33) is a member of the IL-1 family contributing to pathogenesis in allergic lung diseases, atopic dermatitis, sepsis, inflammatory tendinopathy but also to rheumatoid arthritis and psoriasis." (PMID 28702024, 2017).
atopic dermatitis (continued). "For example SDC-4 (syndecan-4) mRNA levels were increased in atopic dermatitis compared with normal skin samples and the inflammatory mediators IL-17, IL-20, IL-24, IL-31, and IL-33 were also elevated in atopic dermatitis." (PMID 29383128, 2017). "Previous studies found that the expression of TNF-α and IFN-γ can induce the expression of IL-33 to promote allergic dermatitis." (PMID 28751921, 2017). "Interleukin-33 is a relatively newly described cytokine, which holds a promising potential as a biomarker for different diseases including atopic dermatitis." (PMID 26788445, 2016). "Cutaneous mastocytosis is a common feature of atopic dermatitis in humans and also in murine models, such as skin-specific caspase-1 transgenic (tg) mice and IL-33 tg mice." (PMID 26549942, 2015). "IL-33 activates the Th2-type immune response and pro-inflammatory cytokines, which are elevated in serum and tissue in atopic dermatitis 24,25, chronic asthma 5,26, and allergic rhinitis 27–29." (PMID 26417437, 2015). "hK14mIL33tg mice in which IL-33 is expressed under the keratin 14 promoter developed spontaneous atopic dermatitis-like inflammation of the skin at 6–8 weeks of age in specific pathogen-free (SPF) conditions." (PMID 25427661, 2014). "The expression of IL33 is increased in human patients with atopic dermatitis and in mouse models of atopic dermatitis." (PMID 24465642, 2014). "It has been shown that IL-33 mounts potent Th2 inflammatory responses and induces the degranulation of IgE-sensitized mast cells in skin, resulting in exacerbation of atopic dermatitis." (PMID 24586149, 2014). "In contrast, a separate report demonstrated that overexpression of IL-33 in the skin led to atopic dermatitis-like pathology including increased dermal eosinophils, increased Th2 cytokines and expansion of skin ILC2." (PMID 24876829, 2013). "GSVA revealed MC IL‐4 + IL‐13 signatures enriched in atopic dermatitis and psoriasis, IFNγ in COVID‐19 infection and cystic fibrosis, IL‐33 in COVID‐19 and chronic obstructive pulmonary disease (COPD) and TGFβ in pulmonary fibrosis (PF) and chronic rhinosinusitis." (PMID 40926620, 2025). "The role of interleukins IL-4, IL-5, IL-10, IL-13 and IL-33 in atopic dermatitis." (PMID 40771803, 2025). "These interactions are pivotal in the development of skin inflammation, as demonstrated by studies indicating that IL-33 can induce skin inflammation with mast cell and neutrophil activation, suggesting a broad immunological role of IL-33 in conditions like psoriasis and atopic dermatitis." (PMID 38396704, 2024). "Despite having reported to be increased in other skin conditions such as vitiligo and atopic dermatitis, IL-33 elevation was significantly higher in psoriatic than in AD lesions, hence lesional IL-33 seem to correlate strongly with psoriasis in a localized manner." (PMID 37546687, 2023). "Moreover, calcitriol treatment reversed the decrease in the expression of skin barrier-related proteins and decreased the expression of inflammatory cytokines such as interleukin (IL)-13 and IL-33 in mice with atopic dermatitis." (PMID 37298299, 2023). "In this context, the alarmin known as interleukin-33 (IL-33), traditionally involved in allergic and autoimmune diseases (such as rheumatoid arthritis, systemic sclerosis, atopic dermatitis and food allergies), assumes a role of particular interest, as it is involved in pro-inflammatory processes." (PMID 35327516, 2022). "We considered whether the ACE2 receptor expression in keratinocytes would increase in atopic dermatitis, and whether it would be attributed to the regulation and action of IL-33." (PMID 35625919, 2022). "The importance of IL-33 in the pathogenesis of atopic dermatitis is considerable." (PMID 35386968, 2021). "Levels of IL33 expression correlate with the severity of atopic dermatitis." (PMID 34571811, 2021). "IL-33 protein levels are upregulated in atopic dermatitis patients and in IgE/Ag-stimulated mice." (PMID 34576749, 2021).
atopic dermatitis (continued). "IL-33 is highly expressed in the epidermal keratinocytes in AD, and IL-33 expression in the epidermis is known to correlate with the severity of skin rashes as indicated by SCORing Atopic Dermatitis and Eczema Area and Severity Index." (PMID 34909732, 2021). "Other cytokines, such as IL-4, IL-13, IL-31 and IL-33 play a key role in the pro-inflammatory and anti-inflammatory signaling pathways in patients suffering from inflammatory skin diseases such as psoriasis or atopic dermatitis." (PMID 33467067, 2021). "The expression of TSLP and IL33 is increased in the skin of human patients with atopic dermatitis." (PMID 32687504, 2020). "We also examined whether tapinarof, a potent AHR activator that is utilized clinically in the treatment of psoriasis and atopic dermatitis, has the same effect as Glyteer on IL-4-induced upregulation of IL-33 expression." (PMID 32214018, 2020). "In fact, the use of a chimeric IL2/IL33 protein was shown to be protective in renal injury and monoclonal anti-IL-33 antibodies where shown to excert promising effects in the control of atopic dermatitis." (PMID 30949175, 2019). "Furthermore, Il33 tg mice, which specifically overexpress IL-33 in their keratinocytes, spontaneously develop atopic dermatitis-like chronic cutaneous alterations." (PMID 26549942, 2015). "IL-33 holds a key to understanding the etiology of atopic dermatitis." (PMID 26417437, 2015). "Therefore, targeting IL-33 as an alternative treatment strategy for atopic dermatitis patients should be approached with caution." (PMID 24586149, 2014). "Similarly, the cytokine IL-33 was upregulated in our study and was also shown to play a role in human atopic dermatitis and anaphylaxis." (PMID 25098772, 2014). "The different functions of IL-33 in mast cells and macrophages suggest that IL-33 may play a dual role during S.aureus infection in atopic dermatitis patients." (PMID 24586149, 2014). "The key will be to evoke a reduction in the detrimental aspects of IL-33 without increasing the risk of infection in atopic dermatitis patients." (PMID 24586149, 2014). "Given increased levels of type 2 cytokines, IL-13, IL-4 and IL-5, in acute atopic eczema lesions and enhanced production of epithelial cytokines IL-33, IL-25 and TSLP, it is plausible that group 2 innate lymphoid cells contribute to the pathogenesis of atopic dermatitis." (PMID 25427661, 2014). "The latest studies confirm the expression of IL-33 receptors in atopic dermatitis, but indicate that IL-18 may be of key importance in maintaining the independence of IL-33 activation of ILC2 during skin inflammation, hence the low effectiveness of IL-33 inhibition in atopic dermatitis." (PMID 38672221, 2024). "In addition, a recent study indicated that the sebum-microbial metabolite-IL-33 axis may play a role in initiating atopic dermatitis." (PMID 36911720, 2023). "Therefore, IL-33 is one of the crucial cytokines in both atopic dermatitis and in COVID-19." (PMID 35625919, 2022). "There is the possibility that direct contact of skin with these allergens could trigger signals to initiate a Th2 allergic response and that the epithelial cell-derived cytokines such as TSLP, IL-33, and IL-25 may drive the progression from atopic dermatitis to bronchial asthma." (PMID 33806376, 2021). "Such an upregulation of IL-33 was not seen in the RNA-seq analysis performed on primary keratinocytes from a different person, indicating variability in the human population, such as is seen with atopic dermatitis susceptibility." (PMID 33028686, 2020). "However, it is unknown whether this dual role of IL-33 exists in other skin diseases, such as atopic dermatitis." (PMID 24586149, 2014). "- Atopic dermatitis is primarily Th2-driven, characterized by IL-4, IL-13, TSLP, and IL-33, promoting eosinophil and mast cell infiltration." (PMID 41479908, 2025). "In IL‐33 transgenic mice, basophils activate ILC2 cells to induce inflammatory processes such as atopic dermatitis." (PMID 39654685, 2024).
atopic dermatitis (continued). "The current evidence and advances for the potential treatment of atopic dermatitis have been studied by targeting specific interleukin (p.e IL1, IL33), common in both inflammatory pathways pain in atopic dermatitis." (PMID 38400917, 2024). "The expression levels of IL-33 and TSLP obviously increased in the back skin of mice with atopic dermatitis induced by HDM treatment." (PMID 36077570, 2022). "Literature has indicated that IL-33/ST2 is involved in the nosogenesis of a wide range of skin diseases, including atopic dermatitis and psoriasis." (PMID 35909659, 2022). "We previously generated a transgenic mouse line expressing skin-specific IL-33 (IL33tg mice) and showed that IL-33 elicits group 2 innate lymphoid cell (ILC2)–dependent atopic dermatitis–like skin inflammation." (PMID 34909732, 2021). "The expression of Th2-inducing cytokines, such as TSLP (thymic stromal lymphopoietin), IL33, and IL25, is increased in atopic dermatitis, and other Th2-mediated disorders." (PMID 34571811, 2021). "IL33 can activate ILC2 to produce type 2 cytokines in models of allergic asthma and atopic dermatitis." (PMID 28742815, 2017). "The direct application of HDM extracts in skin of AD patients with histories of HDM allergy induced IL-33 and ST2 expressions suggesting a key role for IL-33-ST2 interaction in the pathogenesis of atopic dermatitis." (PMID 23724247, 2013). "Notably, PIEZO2hi fibroblasts highly expressed IL33 and POSTN, genes involved in the pathogenesis of itch in atopic dermatitis, while they showed a relatively lower expression of genes associated with chemical itch than did PIEZO2lo fibroblasts." (PMID 40742741, 2025). "IL-33 is released along with TSLP by keratinocytes in response to skin barrier damage and inflammation observed after mechanical injury and scratching or in atopic dermatitis." (PMID 36904070, 2023). "ST36 is effective in regulating itching in various dermatitis diseases, including atopic dermatitis, and its representative mechanisms include negative feedback action on IL-33 and inhibition of mast cell degranulation." (PMID 34527063, 2021). "In Th2 hapten TDI-sentitized allergic dermatitis model mice, oral or topical administration of ERα agonist propylpyrazoletriol induced TSLP and IL-33 expression in keratinocytes and promoted scratching behavior; the pruritus might be caused by TSLP and IL-33." (PMID 31547021, 2019). "However, increase levels of Il33 expression are found in patients suffering from chronic obstructive pulmonary disease (COPD), graft-versus-host disease (GVHD) and atopic dermatitis at sites of inflammation." (PMID 31574995, 2019). "In humans, both IL-33 mRNA and protein are substantially elevated in the inflamed skin lesions of atopic dermatitis (AD) patients when compared with non-inflamed skin." (PMID 30886621, 2019). "Instead, the role of IL-33 in atopic dermatitis has not been clarified; it seems that IL-33 in skin can convert an innocuous antigen exposure into an allergen sensitization leading to a skin reaction." (PMID 29713240, 2018). "IL-33 mRNA and protein is also substantially higher in the skin lesions of patients with atopic dermatitis compared with non-inflamed skin samples, and in affected psoriatic skin compared to healthy skin." (PMID 21871091, 2011). "Finally, the beneficial effect of statins in blocking the TBK1-IRF3-IL-33 axis may also extend to other IL-33-dependent chronic inflammatory conditions, including chronic obstructive pulmonary disease (COPD), atopic dermatitis, and asthma." (PMID 38816352, 2024). "There is an especially close link between IL-33 and atopic dermatitis: while efficacy of anti-IL-33-tageted therapies is still not completely defined, etokimab (a therapeutic anti-IL-33 antibody) showed improvement in skin score and reduced skin neutrophil infiltration after a single administration." (PMID 38067128, 2023).
atopic dermatitis (continued). "In an atopic dermatitis-like murine model of skin inflammation, oral heat-killed YRC3780 administration alleviated allergen-induced dermal responses and decreased the expression of IL-4 and IL-33 in CD4+ T cells in the Peyer’s patches and draining lymph nodes, respectively." (PMID 36422599, 2022). "It is noteworthy that levels of IL-33 which has been shown to play a crucial role in atopic dermatitis are decreased indicating that ILC2 might not be drivers of the remodeling condition in the NSG-UC." (PMID 29282132, 2017). "The receptors for IL-31, IL-31RA, and the receptor for IL-33, ST2, are commonly expressed on dermal fibroblasts, and it is speculated that IL-31 and IL-33 can synergistically stimulate basophils that interact with fibroblasts to release atopic dermatitis (AD)-related chemokines." (PMID 35634336, 2022). "Another group utilized a mouse model of TSLP-driven atopic dermatitis and demonstrated that ILC2 activation occurs independent of IL-33, but is dependent on TSLP receptor signaling." (PMID 24876829, 2013).